SNORA41B (small nucleolar RNA, H/ACA box 41B)
Gene: Small nucleolar RNA gene on chromosome 15 (45,537,250 to 45,537,377, forward strand). Ensembl gene ENSG00000207516.
Gene Ontology:
Biological process: RNA processing
Cellular component: nucleolus
Homologues: Orthologues: chimpanzee SNORA41B (100% identical), macaque SNORA41B (99% identical), rat Snora41b (84% identical), rat LOC120100369 (81% identical), mouse Gm25409 (80% identical). Paralogues in human: SNORA41 (88% identical).